KRAS (KRas proto-oncogene, GTPase)
Diseases named in the same sentence as KRAS in open-access papers (continued):
Sharing a sentence is not in itself a finding about the gene and the disease.
cancer (continued). "Cancer cells harboring the KRAS G12C mutation entered a quiescent state, in which some of the cells died, while others were able to overcome this inhibition through the synthesis of new KRAS G12C proteins that can be rapidly activated through the upstream effectors EGFR and AURKA." (PMID 40597785, 2025). "KRAS oncogenic mutations account for approximately 25% of all human cancers." (PMID 40344393, 2025). "Other genes, such as RYR2 and ANO1, both related to KRAS Signaling in the MSigDB “Hallmark Gene Sets”, were proposed for the hallmark of “Sustaining Proliferative Signaling”, underscoring their role in uncontrolled cell proliferation, a hallmark of cancer." (PMID 40136626, 2025). "Notably, 98.28% of KRAS mutations were missense, which play a crucial role in cancer development and progression, making them valuable potential biomarkers." (PMID 40422048, 2025). "Additionally, given the dramatic interplay between KRAS-mutated cancer cells and the immune-suppressive microenvironment, the addition of KRAS G12C inhibitors to (chemo) immunotherapy treatment constitutes a biologically sound approach." (PMID 40940900, 2025). "The oncogene KRAS, which is pathogenic in various cancers, is a member of the RAS gene family." (PMID 40303413, 2025). "The pathway may be activated by cytokines and growth factors secreted by CAFs, such as COX2 (PTGS2)/PEG2 (PTGER2) or IL6 which were up‐regulated in PM CMS4, or through pathway‐related genetic mutations in the cancer cells, such as KRAS mutations." (PMID 39739693, 2025). "However, clinical applications of these KRAS inhibitor compounds are limited to specific cancer types which carry the relevant KRAS mutations." (PMID 39820726, 2025). "Notably, the FDA approval of allele-specific KRAS G12C inhibitors has marked a significant milestone in the therapeutic strategies to target RAS-mutant cancers." (PMID 40597785, 2025). "KRAS mutations may have multiple co-mutations, which can sometimes affect the functions of KRAS and the emergence and progression of tumors, along with the various mutation subtypes and mutation levels of various cancer tissues." (PMID 40075634, 2025). "Notably, cancer cells harboring KRAS mutation highly expressed glucose transporters and glycolytic enzymes, leading to rapid anerobic glycolysis to produce lactate." (PMID 40707783, 2025). "Unlike uterine bleeding associated with non-ovulatory circumstances, retrograde menstruation following an ovulation maximizes shedding of epithelial cells localized to deep invaginations of the basalis portion of the endometrium, which likely carry somatic cancer-driver mutations such as KRAS." (PMID 40590223, 2025). "For example, some of the most recurrent coding neomers were the result of either the Gly12Asp, Gly12Val, or Gly12Cys missense mutation in the KRAS proto-oncogene GTPase (KRAS), which are known to make up 80% of cancer-associated KRAS mutations and lead to KRAS being constitutively active." (PMID 40841759, 2025). "KRAS mutations are a key driver of oncogenic alterations in various cancers,particularly in PDAC." (PMID 41394580, 2025). "SIAH3 appears to be an attractive target for further investigation as its active homologs, SIAH1 and SIAH2, are known to be downstream effectors of the KRAS pathway and have been shown to be associated with cancer progression and poor prognosis in multiple cancers." (PMID 40243415, 2025). "Our findings may provide insight into the common transcriptional signatures potentially underlying colon and pancreatic KRAS‐mutant cancers." (PMID 40013338, 2025).
cancer (continued). "When the mutant KRAS allele undergoes amplification, the increased gene copy number can lead to elevated expression of the mutant protein, further enhancing downstream signaling activity and promoting cancer progression." (PMID 40427213, 2025). "Moreover, KRAS/SMARCA4 co-mutated patients across multiple NSCLC studies were found to have inferior survival outcomes throughout various types of cancer treatment analysis, including chemotherapy, ICI, and targeted therapy." (PMID 41007704, 2025). "Clinical trials have shown that KRAS G12C inhibitors may play a crucial role in treating cancer patients harboring the KRAS G12C mutation." (PMID 40597785, 2025). "Oncogenic KRAS mutations underlie some of the deadliest human cancers." (PMID 40859018, 2025). "Notably, KRAS mutations not only drive oncogenic signaling but also lead to substantial alterations in the epigenetic landscape of cancer cells." (PMID 39806421, 2025). "In addition, recent studies have noticed that co-mutations with KRAS also play a pivotal role in the oncogenesis and immune landscape of tumors, making them a significant focus for cancer research and therapy." (PMID 40611261, 2025). "cfDNA originates from apoptotic or necrotic cells and serves as an important biomarker for cellular damage, while ctDNA is derived from cancer cells undergoing apoptosis or necrosis and may contain cancer-specific gene mutations, such as KRAS." (PMID 40741141, 2025). "The pattern of KRAS mutation varies considerably across various cancer types." (PMID 40075634, 2025). "Similarly, hyperactivation of the PI3K-AKT pathway contributes to metabolic reprogramming, increased survival, and therapeutic resistance, highlighting the potential value of dual targeting of MAPK and PI3K in KRAS-mutated cancer." (PMID 41309533, 2025). "Mutant KRAS has been implicated in driving a quarter of all cancer types." (PMID 40762837, 2025). "KRAS mutations are implicated in approximately 25% of human cancers." (PMID 38536652, 2025). "Additionally, WEE1 inhibitors also demonstrate synergistic effects with various targeted therapies in KRAS-mutated cancers." (PMID 40885709, 2025). "However, KRAS-mutated cancers are still relatively heterogenous, and thus additional biomarkers are necessary to accurately predict treatment responses." (PMID 41226343, 2025). "Although the detailed mechanism is waiting to be elucidated, as a significant character of a subgroup of KRAS-mutated cancer cells, KEAP1 could have a crucial role in shaping global characteristics, or at least as a substantial component." (PMID 40611261, 2025). "Preclinical studies showed that ASP3082 induced degradation of KRAS G12D protein, inhibition of KRAS downstream proteins, and an apoptotic response, and exhibited potent dose-dependent antitumor activities in multiple KRAS G12D-mutated cancer models (PDAC, CRC, and NSCLC)." (PMID 40597785, 2025). "Both cancers share common features, such as some KRAS pathogenic variants and common epidemiology." (PMID 40013338, 2025). "Notably, pembrolizumab and nivolumab, previously discussed as monoclonal antibodies, overlap with this category, as they release the brakes on T cells and are very effective against oncogene-driven cancers that have mutations in genes like KRAS and EGFR." (PMID 40149342, 2025). "Monoallelic variants in KRAS cause uncontrolled cell division, leading to cancer development." (PMID 41155822, 2025). "Moreover, Adagrasib and Sotorasib inhibit KRAS G12C mutations, leading to the blockage of cancer cell growth in patients with a specific genetic mutation." (PMID 40075700, 2025). "YAP1 is implicated as a driver of resistance in KRAS-mutant cancers." (PMID 41193428, 2025). "This is particularly interesting and might pave the way to the development of alternative new therapeutic peptides for KRas‐mutated cancer types." (PMID 40270247, 2025).
cancer (continued). "Pin1 has been shown to play a major role in modulating protein function, and its overexpression is implicated in the onset and progression of several cancers, activating several oncoproteins, such as those in the KRAS pathway, while simultaneously inactivating tumor suppressors." (PMID 41322199, 2025). "This may represent a potential avenue for preventive treatment in high‐risk KRAS‐associated cancer patients, though it seems there is still a long and winding road ahead." (PMID 40485603, 2025). "Additionally, ME1-driven glutaminolysis is associated with KRAS mutations, which are a metabolic phenotype associated with cancer stem cells (CSCs) and are emerging as a potential therapeutic target." (PMID 39996805, 2025). "KRAS is a growth-regulatory GTPase that is frequently mutated in many cancers." (PMID 40779492, 2025). "Furthermore, given that KRAS mutations are widely reported in several cancer types, exploring the role of CREPT in regulating mutation-induced activation of MAPK signaling in these other cancers remains an intriguing avenue for future research." (PMID 40860160, 2025). "Similarly, genetic silencing by RNA interference (RNAi) in KRAS-mutant human cancer cell lines also caused growth suppression." (PMID 40829181, 2025). "Furthermore, KRAS mutations reprogram cancer metabolism, enhancing glycolysis, macropinocytosis, and autophagy, which are being explored therapeutically." (PMID 40805153, 2025). "Additional Cancer Hotspot analyses showed distinct somatic pathogenic variants in KRAS and TERT." (PMID 40956995, 2025). "Importantly, the most frequently mutated residues in KRAS-driven cancers—codons 12, 13, and 61—are situated within or adjacent to these regions." (PMID 40611261, 2025). "KRAS mutation can assist cancer cells to counterattack T cells." (PMID 40611261, 2025). "Indeed, KRAS WT amplification status (CN > 7) was the most significant single genetic alteration associated with response to BI-2493 in a large cancer cell line panel." (PMID 39711431, 2025). "Moreover, our findings provide an overview of the expression trends of relevant cancer‐related genes (in the tissues and cell lines associated with the analyzed tumors), considering the distinct mutational status of KRAS." (PMID 40013338, 2025). "However, FSs prioritize molecules consistent with the cellular plasticity traditionally associated with KRAS‐driven cancers." (PMID 40013338, 2025). "Overall, the lower VAF observed in MCNs suggest a trend towards reduced mutation levels compared to PDAC, implying that the abundance of KRAS mutations may represent a key feature of cancer progression." (PMID 39906959, 2025). "Furthermore, pharmacologic targeting of MEK as a down-stream target of KRAS has been shown to be effective in multiple KRAS-mutated malignant tumors." (PMID 40519304, 2025). "KRAS mutations are one of the most thoroughly studied targets for cancer therapy." (PMID 40970755, 2025). "Monoclonal antibodies (mAbs), immune checkpoint inhibitors (ICI), cytokine therapy, cancer vaccines, and CAR-T cell therapy are the commonly available immunotherapies that could be harnessed to combat KRAS mutated cancers." (PMID 39453574, 2024). "Cancer stage was predictive of survival, particularly in patients with KRAS mutations." (PMID 39385301, 2024). "KRAS mutations were more prevalent in particularly borderline ovarian tumors than malignant tumors." (PMID 38730733, 2024). "By targeting HSF1, it may be possible to exploit this stress vulnerability, making KRAS-mutant cancer cells more susceptible to therapeutic intervention." (PMID 39850800, 2024). "Notably, KRAS mutations (G12, G13 or Q61) are often identified in various cancers such as lung, pancreatic, colorectal, and certain types of leukemia." (PMID 38982514, 2024). "Additionally, the data provided herein suggests that a monoclonal antibody, in a similar sense as other anti-KRAS mAbs and pAbs29,35–37, is taken up by KRAS-mutated cancer cells by macropinocytosis." (PMID 39179604, 2024).
cancer (continued). "An alternative intrinsic resistance mechanism could be the intratumour heterogeneous distribution of KRAS mutations within the same cancer, leading to the presence of non-G12C clones." (PMID 38347643, 2024). "Additionally, the expression of GFRA3 in GC has been correlated with the activation of two cancer-associated pathways: the KRAS signaling pathway and epithelial–mesenchymal transition (EMT)." (PMID 39767561, 2024). "In the case of pancreatic cancer, the mutation of KRAS plays a critical role in cancer initiation and progression, which could be readily detectable at Stage 1 pancreatic intraepithelial neoplasia (PanIN)." (PMID 39056802, 2024). "Taken together, these findings may suggest that the expression and methylation levels of the genes SLC30A10 and SLC30A3 may have predictive value for the sensitivity of cancer cells to platinum drugs, also inthe case of KRAS-mutated CRC cells." (PMID 39596116, 2024). "Because RMC-6236 targets the active, GTP-bound form of RAS proteins, we hypothesized that RMC-6236 may be more active in cancer cells with KRAS-mutant allele copy-number gain than those inhibitors targeting the GDP-bound form of RAS proteins." (PMID 38593348, 2024). "KRAS, as a widely acting gene, frequently undergoes mutations in various cancers." (PMID 39013849, 2024). "KRAS is a small GTPase that ranks among the most commonly mutated oncogenic drivers in cancer." (PMID 38668053, 2024). "Similarly, KRAS mutations, particularly the pathogenic c.35G>T (p.Gly12Val) variant identified in this study, are well-known drivers of cancer and are associated with resistance to certain therapies, such as anti-EGFR monoclonal antibodies." (PMID 39296440, 2024). "On the other hand, lower availability of copper suppresses the growth of KRAS-mutated cancer cells." (PMID 38662225, 2024). "Furthermore, vigorous Mitogen-activated protein kinase (MAPK) signaling driven by gain-of-function mutations in KRAS is a common genetic feature of cancer." (PMID 39074091, 2024). "KRAS is among the most frequently mutated genes in human cancers." (PMID 38796063, 2024). "We also noticed that the KRAS signaling pathway, which was the only upregulated pathway identified in cluster-3, is the most frequently mutated oncogene in human cancers, with mutations identified in approximately 30% of all cancers." (PMID 38693353, 2024). "These recurring keywords not only reflect the primary research focus on KRAS mutations and immunotherapy in cancer but also provide insights into methodological aspects (“open-label”) and other molecular facets (“expression,” “clathrate”) that are pertinent to this line of inquiry." (PMID 39252322, 2024). "There is a correlation between excessive body weight and cancers that carry a KRAS mutation." (PMID 39031216, 2024). "Interestingly, CRC distinguishes itself with its diverse array of alleles among the “big 3” cancers known for their high prevalence of KRAS mutations." (PMID 39164274, 2024). "Similarly, miR-21 also affects cancer cells’ response to cetuximab and can potentially overcome the KRAS mutation, a major genetic cause of cetuximab resistance." (PMID 38891080, 2024). "KRAS mutations have critical roles in the etiology of cancers such as NSCLC, CRC, and PDAC." (PMID 39001451, 2024). "We hypothesize that KRAS mutations can push cells to a similar glyco-phenotype independent of the cell of origin, given that it is an oncogenic driver commonly found in both cancer types." (PMID 38384845, 2024). "KRAS is the most frequently mutated oncogene accounting for approximately 25% of all human cancers." (PMID 38978742, 2024). "Due to the high frequency of KRAS alterations in human malignancies, these findings could be extended to potentially provide a significant clinical benefit across a broad cancer patient population with KRAS mutation." (PMID 38409090, 2024).
cancer (continued). "However, exogenously introduced KRAS G13D in the PIK3CA-mutated cancer cell leads to drug resistance." (PMID 39056802, 2024). "KRAS is the most frequently mutated driver oncogene in ~ 20% of all types of cancer." (PMID 38992694, 2024). "Some cancer cells develop non-G12C KRAS mutations, resulting in resistance to KRAS inhibitors." (PMID 38655260, 2024). "Due to a variety of cancer cell-intrinsic factors, including KRAS mutations, chemokine production, and other mechanisms that elicit a dysregulated host immune response, PDAC is often characterized by poor immune infiltration and an immune-privileged fibrotic stroma." (PMID 39518557, 2024). "However, our findings strongly suggest that in mutant KRAS-associated cancer, the complex substantially increases the efficiency of nuclear protein export." (PMID 39528835, 2024). "While there have been advancements in the development of small molecules to target specific KRAS mutants, the presence of undruggable mutants and the emergence of secondary mutations continue to pose challenges in the clinical treatment of KRAS-mutant cancers." (PMID 38937452, 2024). "The cell culture and animal model study of different types of KRAS mutations noticed different signaling pathways, which could be the probable reason for the different intensities of cancer pathology associated with KRAS mutations." (PMID 39056802, 2024). "PD-L1/PD-1-mediated immune evasion is observed in several KRAS-mutated cancers." (PMID 39201772, 2024). "KRAS mutations are even present in 85% of all RAS-mutant cancers." (PMID 38397927, 2024). "KRAS mutations are also present in rare cancers, revealing a general mutation rate of 8.7%." (PMID 39164274, 2024). "All seven SMARCA4/KRAS co-mutation NSCLC publications in this review showed either a significantly worse PFS or OS as compared to SMARCA4 WT/KRAS mutation analyses across standard-of-care cancer treatments or within a specific treatment analysis (i.e., KRAS G12C inhibitor, ICIs, or non-ICIs)." (PMID 39063938, 2024). "Single-point mutations in KRAS are the most common cause of human cancer." (PMID 38794122, 2024). "Therefore, we took advantage of this vulnerability to dissect the specific regulatory site/s of FAK required for the maintenance of KRAS mutated cancer cells." (PMID 39271958, 2024). "In addition, the investigators discovered that the same cancer gene showed different mutations in different tumors of one patient (KRAS mutation in P1: T1 p.G12A, T3 p.G12V; EGFR mutation in P4: T1 p.L858R, T2 p.S229C)." (PMID 39411141, 2024). "Studies have shown that the cooperation of LKB1 deficiency and GTPase KRas (KRAS) activation could promote cancer progression through the mTOR-dependent induction of the serine–glycine one-carbon pathway, leading to increased SAM production." (PMID 38535331, 2024). "In conclusion, targeting MAP3K2 in KRAS-mutated cancer cell lines could affect cellular growth and viability, making it a potential SL pair for further in vitro and in vivo confirmation." (PMID 37863651, 2024). "KRAS is a small GTPase that is among the most commonly mutated oncogenes in cancer." (PMID 38668053, 2024). "RAS proteins are among the most frequently mutated in solid tumors, and targeted therapies against the activating mutation KRAS G12C are clinically active for various solid tumors including non-small-cell lung (sotorasib and adagrasib) and pancreatic (sotorasib) cancers." (PMID 38672653, 2024).